F13A1 (coagulation factor XIII A chain)
Description:
Factor XIII is activated by thrombin and calcium ion to a transglutaminase that catalyzes the formation of gamma-glutamyl-epsilon-lysine cross-links between fibrin chains, thus stabilizing the fibrin clot. Also cross-link alpha-2-plasmin inhibitor, or fibronectin, to the alpha chains of fibrin.
Synonyms: F13A
Tractability: Small molecule: a high-quality ligand is known; it has a high-quality binding pocket; it belongs to a druggable protein family. Antibody: UniProt places it where antibodies can reach, with high confidence; its Gene Ontology location is reachable by antibodies, with high confidence. PROTAC: its protein half-life has been measured; a small molecule that binds it is known. Other modalities: an approved drug acts on it.
Target class: Protein-glutamine glutamyl-transferase; Enzyme; Aminoacyltransferase
Gene: Protein-coding gene on chromosome 6 (6,144,080 to 6,321,013, reverse strand). Ensembl gene ENSG00000124491.
Subcellular location: Cytoplasm; Secreted
Pathways (Reactome):
Hemostasis: Fibrin formation; Platelet degranulation
Immune System: Interleukin-4 and Interleukin-13 signaling
Gene Ontology:
Molecular function: protein binding; protein-glutamine gamma-glutamyltransferase activity
Biological process: blood coagulation, fibrin clot formation; peptide cross-linking; blood coagulation
Cellular component: blood microparticle; extracellular matrix; extracellular region; platelet alpha granule lumen; transferase complex; cytoplasm
Genetic constraint (gnomAD): Loss-of-function variants: 48 observed, 83.19 expected, observed/expected ratio (o/e) 0.58, 90% interval 0.46 to 0.73. The upper end of that interval is the gene's LOEUF score, 0.73, which puts it in group 3 of 6, group 1 being the genes least tolerant of losing a copy. Missense variants: 808 observed, 969.68 expected, observed/expected ratio (o/e) 0.83, 90% interval 0.79 to 0.88. Synonymous variants: 346 observed, 360.38 expected, observed/expected ratio (o/e) 0.96, 90% interval 0.88 to 1.05.
Gene-disease validity (ClinGen):
ClinGen rates the evidence that F13A1 causes each of these diseases.
factor XIII, A subunit, deficiency of (autosomal recessive): Definitive.
Homologues: Orthologues: chimpanzee F13A1 (99% identical), macaque F13A1 (97% identical), dog F13A1 (88% identical), mouse F13a1 (87% identical), rat F13a1 (86% identical), pig F13A1 (86% identical), guinea pig F13A1 (85% identical), tropical clawed frog f13a1 (63% identical), zebrafish f13a1b (47% identical), zebrafish f13a1a.1 (41% identical), Drosophila melanogaster Tg (33% identical), zebrafish F13A1 (33% identical). Paralogues in human: TGM1 (42% identical), TGM2 (35% identical), TGM6 (33% identical), TGM5 (33% identical), TGM3 (32% identical), TGM4 (29% identical), TGM7 (29% identical), EPB42 (24% identical).
Diseases named in the same sentence as F13A1 in open-access papers:
F13A1 is named in the same sentence as 97 diseases in open-access papers, as found by Europe PMC text mining. Sharing a sentence is not in itself a finding about the gene and the disease. The quoted sentences say what the papers report.
lung carcinoma (10 papers, 2019 to 2025). "These new data on the differential behaviour of platelets in various cancers revealed F13A1 and ER chaperones as potential novel diagnostic and therapeutic targets in lung cancer patients." (PMID 34066760, 2021). "Elevated expression of F13A1 in inflammatory monocytes of lung squamous carcinoma patients enhances fibrin cross-linking, promoting lung cancer cell metastasis." (PMID 40002669, 2025). "For pathophysiological explorations of platelet proteome changes in patients with lung cancer we concentrated on four candidates described to be involved in the processing of coagulation proteins, which are F13A1 and the ER proteins P4HB, CALR and HSPA5." (PMID 34066760, 2021). "Plasma F13A1 activity was unchanged in patients with lung cancer and was significantly decreased in patients with brain cancer." (PMID 34066760, 2021). "High F13A1 expression in lung cancer patients may contribute to tumor metastasis by hindering the clearance of micrometastatic tumor cells mediated by NK cells." (PMID 40002669, 2025). "However, enzymatic F13A1 activity significantly correlated with the levels of F13A1 spots 12b (pI 5.75), 12 (pI 5.60) and 12a (pI 5.65), the abundances of which were significantly increased in patients with lung cancer." (PMID 34066760, 2021). "High expression of F13A1 was also observed in inflammatory monocytes of patients with lung squamous carcinomas, which promote fibrin cross-linking and in turn facilitate metastases of lung carcinoma cells." (PMID 34066760, 2021). "Our findings that the platelet level of the 55 kDa fragment of F13A1 did not correlate with the enzymatic activity of this transglutaminase in platelets suggests that it may be a product of accelerated F13A1 inactivation in patients with lung cancer." (PMID 34066760, 2021). "For example, lung cancer-specific surface markers, such as Complement factor H-related protein 4 (CFHR4) and Coagulation factor XIII A chain (F13A1)." (PMID 38052753, 2023). "F13A1 is widely regarded as a cancer-related gene and FDA-approved drug target that is involved in lung cancer, oral squamous cell carcinoma, and colorectal cancer, consistent with our results." (PMID 36471393, 2022). "F13A1 might be also involved in the development of VTE, as well as in lung cancer progression, and especially this patient group may benefit in multiple ways from antithrombotic treatments such as FXIII inhibitors." (PMID 34066760, 2021). "(ii) The conserved upregulation of TAM-promoting genes (e.g., Arg1, Mrc1 and F13a1) across tumour types suggests that SFV-based therapies could have broader applicability in reprogramming TAMs in other malignancies, such as glioblastoma or lung cancer." (PMID 40547518, 2025). "The significant downregulation of coagulation factor XIII A chain (F13A1) and upregulation of the complement factor H-related protein 4 (CFHR4) in SCLC compared to HCs has not yet been identified in other cancers, including lung cancer." (PMID 34996345, 2022).
COVID-19 (8 papers, 2021 to 2025). A disease caused by infection with severe acute respiratory syndrome coronavirus 2. "In the COVID-19 group, coagulation factor XIII A chain (F13A1) and contactin associated protein 2 (CNTNAP2) exhibited the strongest upregulation, with CD14, C1QC, cytochrome C oxidase subunit 7C (COX7C) and (APOE) being increased in the AD group." (PMID 36211330, 2022). "Coagulation is a feature of COVID-19, and it has been shown that consumption of the coagulation factor XIIIA (F13A1) was elevated in COVID-19 patients and tended to be higher in nonsurvivors." (PMID 40980495, 2025). "Higher consumption of fibrin-stabilizing factor, i.e., coagulation factor XIIIA (F13A1), in platelets was found in COVID-19 patients." (PMID 35453523, 2022). "Consumption of the fibrin-stabilizing factor coagulation factor XIIIA (F13A1) was higher in platelets from COVID-19 patients and tended to be higher in non-survivors; plasma concentrations of the latter also differed significantly." (PMID 34859078, 2021).
myocardial infarction (6 papers, 2018 to 2025). Gross necrosis of the myocardium, as a result of interruption of the blood supply to the area, as in coronary thrombosis. "The activity of F13A1 and coagulation factor XIII (FXII) plasma can affect the risk for myocardial infarction." (PMID 35096131, 2022). "Variations in the F13A1 gene that gives the active subunit of Factor XIII protein are linked to bleeding tendencies (Factor XIIIA deficiency), protection against venous thrombosis, and protection against myocardial infarction." (PMID 29334895, 2018). "F13A1 (FXIII) plays a key role in the coagulation cascade, stabilizing thrombus by cross-linking fibrin and playing a protective role in heart repair after myocardial infarction." (PMID 40305362, 2025).
Obesity (5 papers, 2015 to 2024). Accumulation of substantial excess body fat. "The most significantly different genes included F13a1 and Sema3g, which have previously been associated with adipogenesis and obesity." (PMID 39551140, 2024). "F13A1 gene, which encodes for Factor XIII-A blood clotting factor and a transglutaminase enzyme, was recently identified as a potential causative gene for obesity in humans." (PMID 27759118, 2016). "Interestingly, the coagulation factor XIII, A1 polypeptide (F13A1) was previously identified as a novel obesity candidate gene in humans." (PMID 26445145, 2015).
breast carcinoma (3 papers, 2020 to 2024). "Remarkably, proteins prominently expressed in NmFMC compared with other groups, such as F13A1, CENPF, INSR, SCAF1 and PDK1, have been implicated in human breast cancer, further supporting the potential use of FMC as a model for studying human breast cancer." (PMID 38951817, 2024). "For instance, F13A1 was prominently expressed in human estrogen receptor-negative breast cancer, while targeting CENPF resulted in tumor growth inhibition in human breast cancer." (PMID 38951817, 2024).
colorectal cancer (3 papers, 2018 to 2023). A primary or metastatic malignant neoplasm that affects the colon or rectum. "Because F13A1 (FXIIIA) is one the last factors involved in the coagulation system that catalyse the polymeric Fibrin in cross-linked Fibrin complex, we needed to evaluate the F13A1 protein to get greater insight into coagulation abnormalities in patients with colorectal cancer." (PMID 29657559, 2018). "Besides, F13a1 promotes lung squamous cancer and is a biomarker for colorectal cancers." (PMID 37815040, 2023).
glioblastoma (3 papers, 2017 to 2025). The most malignant astrocytic tumor (WHO grade IV). "F13a1 up-regulation has been reported to be an indicating factor of microglia, adopting a macrophage-like phenotype, as seen in glioblastoma." (PMID 36428550, 2022). "On the other hand, F13a1 is a marker of the M2 repair phenotype in macrophages, and has been reported as an indicator of microglia adopting a macrophage-like phenotype, which was observed in glioblastoma." (PMID 36428550, 2022).
melanoma (3 papers, 2006 to 2023). A malignant, usually aggressive tumor composed of atypical, neoplastic melanocytes. "Moreover, F13A1 and GPC1 are biomarkers for melanoma metastasis." (PMID 37158593, 2023).
Stroke (3 papers, 2014 to 2023). Sudden impairment of blood flow to a part of the brain due to occlusion or rupture of an artery to the brain. "In summarizing this study, we affirm that our risk assessment model, based on PADGs, specifically APP, THBS1, F13A1, SRC, PPBP, and VCL, presents robust diagnostic capabilities for stroke patients." (PMID 38268925, 2023). "In male patients, four of the 34 SVD-associated genes were unique to that specific stroke cause: CYP4F2, GP1BA, solute carrier family four, member one (SLC4A1), and F13A1, which was also uniquely expressed in the male cohort." (PMID 33193047, 2020).
allergic dermatitis (2 papers, 2020 to 2023). "Significant upregulation of F13A1 in allergic horses both during clinical allergy and during remission suggests that IgE-binding monocytes may deposit excess fibrin, enhancing allergic dermatitis and skin inflammation." (PMID 37193769, 2023).
nasal polyps (2 papers, 2021 to 2022). "Expression levels of ALOX5AP, AQP9, CCL13, EMR3, F13A1, GAPT, and NCF2 were significantly higher in nasal polyp samples from ACRSwNP patients compared with the expression levels in samples from healthy subjects." (PMID 36059464, 2022). "The coagulation system dysregulation also plays a role in the tissue remodeling of nasal polyps with reduction of PLAT and upregulation of F13A1." (PMID 35095530, 2021).
ovarian carcinoma (2 papers, 2018 to 2026). A malignant neoplasm originating from the surface ovarian epithelium. "Notably, eight proteins upregulated in the invasive stroma (NNMT, FCGR1A, FCER1G, TYMP, F13A1, DCK, CASP3, and SYK) represented FDA-approved drug targets outside of ovarian cancer, emphasizing their high relevance for future preclinical investigations." (PMID 41233595, 2026).
Allergy (1 paper, 2023). An allergy is an immune response or reaction to substances that are usually not harmful. "Together we report both the coagulation cascade, specifically the genes F13A1, SERPINE1 and C1R, and the CCR10/CCL27 axis, as candidate pathways used by IgE-binding monocytes in the mechanism of allergy." (PMID 37193769, 2023).
anaphylaxis (1 paper, 2022). An acute hypersensitivity reaction that occurs from exposure to an allergen. "Our validation work demonstrated the downregulation of six platelet‐related genes (TLN1, GATA1, SELP, SPARC, MPL and F13A1) in anaphylaxis patients compared with healthy controls." (PMID 36583159, 2022). "Seven genes (TLN1, GATA1, SELP, GP1BA, MPL, F13A1 and SPARC) were also downregulated in patients with severe anaphylaxis who did not receive adrenaline before ED arrival, compared with healthy controls." (PMID 36583159, 2022).
bladder cancer (1 paper, 2020). "In conclusion, high expression of ADRA2A, CXCL12, S1PR1, ADAMTS9, F13A1, and SPON1 was associated with poor overall survival in bladder cancer patients, with a P-value <0.05 considered to be statistically significant." (PMID 32239176, 2020).
colitis (1 paper, 2022). Inflammation of the colon. "RNA-seq data also indicated the significant up-regulation of Cd209d, Wnt9a and F13a1 genes enriched in pathways related to CLR, Wnt and complement and coagulation cascades signaling pathways might be closely related to the effect of CsCA on DSS-induced colitis." (PMID 36084127, 2022).
glioma (1 paper, 2025). A benign or malignant brain and spinal cord tumor that arises from glial cells (astrocytes, oligodendrocytes, ependymal cells). "As fatty acids are key bioenergetic substrates in glioma cells, we built a GBM prognostic model using key fatty acid metabolism genes, highlighting F13A1’s significance." (PMID 40002669, 2025).
hyperlipidemia (1 paper, 2025). "Stratification by disease status and hyperlipidemia revealed that MCL1, F13A1, TLR8, and TAGAP were significantly upregulated in patients with both AS and hyperlipidemia compared with healthy individuals without hyperlipidemia (p < 0.05)." (PMID 41583468, 2025).
hypospadias (1 paper, 2023). Hypospadias is the displacement of the urethral meatus on the ventrum of the penis. "Several of these MeSH terms are associated with TF (transferrin), EGF (epidermal growth factor), MMP14 (Matrix metallopeptidase 14), CDH1 (Cadherin 1), and F13A1 (Coagulation factor XIII A chain) genes, related to CLJ and hypospadias." (PMID 37238140, 2023).
liver cancer (1 paper, 2023). An epithelial or non-epithelial malignant neoplasm that arises from the liver. "Previous global proteomic analysis on small extracellular vesicles identified that F13a1 is associated with liver cancers." (PMID 37815040, 2023). "F13a1 has been known to be associated with various cancers including liver cancer." (PMID 37815040, 2023). "In the liver cancer, Marco (red), Vti1a (green), F13a1 (blue) are largely expressed in Monocyte cells when contacting Hepatocyte I (Monocyte+Hepatocyte I), Hepatocyte II (Monocyte+Hepatocyte II), and Tumor III (Monocyte+Tumor III), respectively." (PMID 37815040, 2023).
lymph node metastasis (1 paper, 2020). "Combined with qPCR-based validation findings from tissue, serum and whole blood samples, they highlighted that serum exosomal proteins, PF4V1, CXCL7, F13A1 and ApoA1 may be related to the OSCC lymph node metastasis." (PMID 32054041, 2020).
non-small cell lung carcinoma (1 paper, 2025). A group of at least three distinct histological types of lung cancer, including non-small cell squamous cell carcinoma, adenocarcinoma, and large cell carcinoma. "Additionally, increased plasma F13A1 activity is also observed in patients with non-small cell lung cancer." (PMID 40002669, 2025).
osteoarthritis (1 paper, 2010). A noninflammatory degenerative joint disease occurring chiefly in older persons, characterized by degeneration of the articular cartilage, hypertrophy of bone at the margins and changes in the synovial membrane. "We focused on F13a1 as an interesting target because of its known role in chondrocyte hypertrophy and osteoarthritis." (PMID 20111593, 2010).
osteosarcoma (1 paper, 2023). A usually aggressive malignant bone-forming mesenchymal neoplasm, predominantly affecting adolescents and young adults. "The results showed that 79 DEGs affected the prognosis of osteosarcoma, with PDE4C, CFAP44, CARNS1, GREB1L, ROF207 identified as significant risk factors and GBP1, MSC, GBP3, F13A1, CCL2 as substantial protective factors." (PMID 37796192, 2023).
periodontitis (1 paper, 2025). An acute or chronic inflammatory process that affects the tissues that surround and support the teeth. "Periodontitis induced the development of GMPs toward the neutrophil lineage at the expense of monocytic differentiation, as indicated by the dynamic changes in monocytic signature genes (F13a1, Irf8, and Ly86) and neutrophil-associated genes (Camk1d, S100a8, and S100a9) along the trajectory." (PMID 40521205, 2025).
preeclampsia (1 paper, 2025). Preeclampsia is a hypertensive disorder of pregnancy that is characterized by new-onset hypertension with proteinuria presenting after 20 weeks of gestation, and depending on mild or severe forms may initially present with severe headache, visual disturbances, and hyperreflexia. "Of all the immune cell-regulated preeclampsia differential genes SLC9A9, SH2B3, SDC3, RCC2, F13A1, CCL2, and CBLB were consistently expressed in two transcriptome datasets, and all were highly expressed in macrophages." (PMID 40216654, 2025). "Lastly, we found that the SLC9A9, SH2B3, SDC3, RCC2, F13A1, CCL2, and CBLB in macrophages were likely to be correlated with preeclampsia." (PMID 40216654, 2025).
skin inflammation (1 paper, 2023). "Therefore, F13A1 overexpression by IgE-binding monocytes of allergic individuals could induce excess fibrin buildup, as monocytes home to skin tissues to heal allergen-induced wounds, leading to dermatitis and scar tissue build-up typically seen in Cul hypersensitivity." (PMID 37193769, 2023).
venous thromboembolism (1 paper, 2010). Occlusion of the lumen of a vein by a thrombus that has migrated from a distal site via the blood stream. "The top hit was SNP rs2274393 (P = 0.003) located in an intron of the 177 kb gene encoding the A1 subunit of the coagulation factor XIII (F13A1), a gene previously associated with the risk of venous thromboembolism." (PMID 20532202, 2010).